SOX9 (SRY-box transcription factor 9)
Diseases named in the same sentence as SOX9 in open-access papers (continued):
Sharing a sentence is not in itself a finding about the gene and the disease.
melanoma (continued). "EMSAs demonstrated that SOX9-NHMG binds to the three elements enriched in melanoma cell DHS in a highly cooperative fashion." (PMID 26013289, 2015). "SOX9 mRNA was expressed robustly in the invasive phenotype melanoma cell cultures compared to the proliferative phenotype melanoma cell cultures (P <0.05)." (PMID 25885555, 2015). "Here, we show that this anti-tumorigenic effect functionally involves SOX9, a factor related to SOX10 and upregulated in melanoma cells upon loss of SOX10." (PMID 25629959, 2015). "We decided to focus on SOX9 for validation due to its known function in melanocyte differentiation and melanoma progression." (PMID 25885555, 2015). "We observed a specific association of SOX9 with TMEM158, TBX3, and FYB, suggesting that TMEM158, TBX3, and FYB are direct targets of SOX9 in melanoma." (PMID 25885555, 2015). "Having identified anti-SOX10 and anti-SOX9 specific antibodies, we reveal virtually exclusive expression patterns of these transcription factors in the normal human skin and in a large set of melanoma biopsies and cell lines." (PMID 25629959, 2015). "To investigate the mRNA expression of SOX10 and SOX9 in a large set of human melanoma samples, we used of the TCGA (The Cancer Genome Atlas) database." (PMID 25629959, 2015). "In our study, a subset of our melanoma cell cultures had lower SOX9 expression due to a hypermethylated promoter and the other subset with high SOX9 expression had a hypomethylated promoter." (PMID 25885555, 2015). "Our discovery of three distinct SOX9 homodimer binding modes in melanoma provides one candidate molecular mechanism for the biological role of this TF in melanoma formation." (PMID 24640962, 2014). "SOX9 expression is upregulated by PGD2, and ectopic SOX9 expression has been shown to suppress growth of ovarian cancer and melanoma cells in vitro and/or in vivo." (PMID 23687991, 2013). "SOX9 and SOX10, overexpressed in melanomas, are implicated in the regulation of genes involved in melanogenesis such as MITF and tyrosinase." (PMID 24086527, 2013). "In human melanoma cells Sox9 has also been identified as an important regulator of Nestin expression." (PMID 21826226, 2011). "As a master regulator of cartilage differentiation, SOX9 regulates expression of various downstream target genes, including collagen type 2a1, collagen type 11a2, aggrecan and melanoma-inhibitory activity (MIA)." (PMID 21726432, 2011). "Another target of PKA could be SOX9 in melanoma cells as it is involved in promoting a cancer stem cell phenotype, contributing to tumour heterogeneity with the crosstalk of SOX10." (PMID 41465475, 2025). "In a mouse model, SOX10 and SOX9 act as antagonistic regulators of melanoma development." (PMID 41465475, 2025). "SOX10 and SOX9 are functionally antagonistic regulators of melanoma development." (PMID 40342816, 2025). "SOX9 causes the direct activation of the microphthalmia transcription factor (MITF) promoter, critical for normal melanocyte differentiation and the modulation of melanoma proliferation." (PMID 38338862, 2024). "The fact that the decrease of SOX9 expression in SKCM and the increase of SOX9 in the cell lines of melanoma inhibit tumorigenicity in both mouse and human ex vivo models demonstrates that SOX9 could also be a tumor suppressor." (PMID 37020558, 2023). "Another report revealed that both PITX1 and SOX9 expressions were reduced in melanoma." (PMID 37841446, 2023). "Thus far, 8 out of 21 GLI targets we chose to validate—KRT16, S100A9, SOX9, BIRC7, EBI3, FLG, SAMMSON and SPRY2—were already implicated in melanoma pathogenesis." (PMID 36139698, 2022).
melanoma (continued). "Melanocyte and NC programs are particularly active in melanoma cells, with increased sox10 and mitfa expression, respectively, seen in the RNA-seq data, and this appears consistent with enrichment of SOX9/10 (SOXE family) and MITF (E/M-boxes) binding sites in more accessible regions in melanoma." (PMID 34791221, 2022). "In addition, integrative analysis reveals that SOX9 is methylated and lowly expressed in the highly proliferative group, and SOX9 overexpression results in decreased proliferation but increased invasion of melanoma cells." (PMID 35693795, 2022). "Interestingly, when we analyzed the expression of NC-specific genes, we found that SOX10– undifferentiated melanoma cell lines had downregulation of genes expressed in normal melanocytes, with the exception of acquired expression of SOX9." (PMID 36040798, 2022). "Therefore, it is likely that SOX9 displays oncogenic and tumor-suppressive functions, suggesting that SOX9 plays a role in switching the phenotype of melanoma cells." (PMID 34526609, 2021). "Moreover, PITX1 mRNA expression level was positively correlated with SOX9 mRNA expression level in human melanoma and normal skin tissues." (PMID 34526609, 2021). "Additionally, induction of PITX1 strongly suppressed SOX10 expression and SAMMSON transcription, which act as oncogenic driver genes in melanoma, via up-regulation of SOX9." (PMID 34526609, 2021). "A possible reason is that SOX9/SOX10 signaling may be disrupted in highly malignant melanoma cells; therefore, it likely plays a more important role in carcinogenesis compared with that in malignancy." (PMID 34526609, 2021). "Moreover, the relative expression of SOX9 was lower in metastatic tissue than in primary melanoma tissue." (PMID 34526609, 2021). "We revealed that further increased SOX9 dosage with comparable expression levels to a range of high SOX9 mRNA detected in malignant melanoma specimens could restore the metastatic properties in SOX10 knockdown cells, partly through induction of NEDD9 activity." (PMID 30642390, 2019). "Thus, the levels of the upregulated SOX9 expression in SOX10 KD melanoma cell lines are similar to the low mRNA levels of SOX9 detected in cutaneous melanoma specimens." (PMID 30642390, 2019). "Altogether, these results suggest that SOX9 OE not only promotes melanoma invasion through modulation of various MMP genes expression but also may have a role in immunosuppression." (PMID 30642390, 2019). "As melanoma acquire invasiveness, the promoter of SOX9 becomes hypomethylated probably through downregulation of DNA methyltransferase that could partly contribute to its high level of expression in a subset of SOX10 negative metastatic melanoma." (PMID 30642390, 2019). "Taken together, these findings suggest that distinct levels of SOX9 expression determine whether it functions as a suppressor or an inducer of melanoma metastasis." (PMID 30642390, 2019). "Thus, we anticipated that SOX10 or high level of SOX9 regulates NEDD9 expression to promote melanoma migration through alteration of focal adhesion dynamics and RHO signaling activity." (PMID 30642390, 2019). "In addition, overexpression of SOX9 can also promote invasiveness of the parental melanoma cells by modulating the expression of various matrix metalloproteinases." (PMID 30642390, 2019). "Indeed, overexpression of SOX9 in both human and mouse melanoma cell lines resulted in inhibition of cell proliferation and tumor growth in xenografts." (PMID 30642390, 2019). "Altogether, our studies provide a molecular explanation to reconcile the previous discrepancies that anti-metastatic role of SOX9 is conferred by its sub-optimal level of expression while a high level of SOX9 is pro-metastatic in a heterogeneous population of melanoma." (PMID 30642390, 2019). "Indeed, qPCR analysis revealed that elevated SOX9 expression was frequently detected in lung and intestine metastatic melanomas compared to the control skin samples from healthy subjects." (PMID 30642390, 2019).
melanoma (continued). "In addition, we further revealed that elevation of SOX9 expression level resulted in downregulation of p21 and restoration of melanoma proliferation and growth." (PMID 30642390, 2019). "The predominant association of SOX10 and NEDD9 but not SOX9 expression in melanoma specimens is further supported by co-expression of these two factors at different levels in a series of malignant melanoma cell lines." (PMID 30642390, 2019). "The discrepancies between the different studies could be attributed to melanoma heterogeneity with distinct expression levels of SOX9 and/or SOX10 in the tumors." (PMID 30642390, 2019). "Additionally, the epigenetic silencing of SOX9 (SRY-Box 9) is responsible for the invasiveness of melanoma." (PMID 27852070, 2017). "Other factors in the nuclei of melanoma cells could compete with SOX9 for the same binding sites, or bind to close areas in the DNA and create a steric interference." (PMID 26885752, 2016). "We assessed ETS1 protein and mRNA expression in melanoma cells after SOX9 silencing." (PMID 26885752, 2016). "SOX9-manipulated melanoma cell lines were used as target cells in cytotoxicity assays." (PMID 26885752, 2016). "However, genes correlated with SOX9 did show relationships to cell lines derived from neural crest (melanoma, glioblastoma) and breast tumors, whose normal tissue and cancer origins are affected by SOX9." (PMID 27880766, 2016). "Finally, functional studies show that knockdown of SOX9 renders melanoma cells more resistant to TIL-mediated killing." (PMID 26885752, 2016). "Indeed, co-immunoprecipitation experiments in several melanoma lines showed that Sp1 physically binds to SOX9." (PMID 26885752, 2016). "Immunoanalysis data revealed that at 7 days of differentiation, TAFH RNAi-treated melanomas showed high levels of expression of chondrocyte-specific SOX9 proteins and prominent staining with Alcian blue that evidenced the synthesis of cartilage-specific ECM-proteins." (PMID 27499390, 2016). "Finally, knockdown of SOX9 indeed renders melanoma cells resistant to T cell-mediated killing, in line with the increased CEACAM1 expression." (PMID 26885752, 2016). "Interestingly, the vast majority of human melanoma samples displayed much higher SOX10 than SOX9 expression and only very few samples were characterized by a SOX9 high / SOX10 low expression pattern." (PMID 25629959, 2015). "However, Sox9 expression is elevated upon Sox10 deletion in mouse and human melanoma cells, and critically contributes to the anti-tumorigenic effects observed upon Sox10 inactivation in giant congenital naevus and melanoma." (PMID 25629959, 2015). "We took advantage of the melanoma dataset and demonstrated that SOX9 expression levels have a significant impact on survival of metastatic melanoma patients but SOX9 did not have a significant impact on survival in patients with primary melanomas." (PMID 25885555, 2015). "To this end, we performed RNAi experiments to test whether interfering with SOX9 overexpression upon SOX10 knockdown could rescue M010817 melanoma cells." (PMID 25629959, 2015). "This could suggest that SOX9 is required for progression of primary melanoma into metastasis and metastatic tumors with high SOX9 are more aggressive to the patient." (PMID 25885555, 2015). "Moreover, SOX10 knockdown also resulted in upregulation of SOX9 protein levels in human melanoma cells." (PMID 25629959, 2015). "To functionally assess the role of SoxE factors in melanomagenesis, we first performed immunohistochemical staining for Sox9 and Sox10 of giant congenital naevi formed in Tyr::NrasQ61K mice and in melanoma derived from giant congenital naevi in Tyr::NrasQ61KInk4a−/− mice." (PMID 25629959, 2015). "From the methylation array, the area that had the most enrichment for methylation was about 2 kb upstream of the SOX9 transcriptional start site thus we validated the CpG island located there via sequencing of bisulfite-treated genomic DNA in the 10 melanoma cell cultures." (PMID 25885555, 2015).
melanoma (continued). "Next, we addressed whether the cross-regulation between SOX10 and SOX9 is functionally relevant in human melanoma cells." (PMID 25629959, 2015). "Overexpression of SOX9 was previously shown to drive melanoma cells into cell cycle arrest." (PMID 25885555, 2015). "Based on these findings and the invasive properties of high SOX9 expressing melanomas, it would suggest that SOX9 expression in melanomas could push the tumor toward more aggressive metastasis." (PMID 25885555, 2015). "Moreover, chromatin immunoprecipitation assays in human melanoma M010817 cells indicated that SOX9 binds to the promoter of SOX10, suggesting a direct regulation of the SOX10 gene by SOX9." (PMID 25629959, 2015). "TBX3 is also upregulated by SOX9 and TBX3 is known to cause increased invasiveness in melanoma, suggesting TBX3 could be an effector gene that drives the invasive phenotype we see in SOX9 high cells and in patients." (PMID 25885555, 2015). "Interestingly, SOX9 is downregulated as melanocytes progress to melanoma, and its overexpression in melanoma cell lines inhibits tumorigenicity." (PMID 24640962, 2014). "Using mutagenesis, co-transfection experiments and chromatin immunoprecipitation, we showed that transcription factors involved in meloe promoter activity in melanomas were the melanocytic specific SOX9 and SOX10 proteins together with the activated P-CREB protein." (PMID 24086527, 2013). "Finally, only SOX9 seemed to be fixed on meloe promoter in the colon carcinoma cell line, to a lesser extend compared with melanoma cells." (PMID 24086527, 2013). "SOX9 is strongly expressed in melanoma cells, but weakly in colon carcinoma cells or mesotheliomas." (PMID 24086527, 2013). "We tested this hypothesis by analyzing expression of the SOX9 target gene product melanoma-inhibitory activity/cd-rap (MIA) in tumour and serum samples of NF1 patients." (PMID 21726432, 2011). "Moreover, high expression of SOX9 is significantly associated with reduced survival rate in adenocarcinoma of the lung (LUAD), squamous cell carcinoma of the lung (LUSC), or melanoma patients." (PMID 32686598, 2020). "The distinct patterns of SOX9 and SOX10 expression in patient specimens probably reflect the heterogeneity of melanoma population harboring different genetic and epigenetic signatures since SOX9 expression could be regulated by DNA methylation and displays antagonistic relationship with SOX10." (PMID 30642390, 2019). "However, SOX9 serves as a tumor suppressor in some melanomas and endometrial carcinoma cells." (PMID 26036262, 2015). "Each of these distal enhancers is positively correlated with both the activity of the SOX9 promoter and its expression levels across the 11 melanoma in-house samples indicating that the distal elements may indeed interact with the SOX9 promoter and regulate SOX9 transcription." (PMID 25865119, 2015). "Also, SOX9 positively regulates p21 expression in melanoma and endometrial carcinoma cells." (PMID 26036262, 2015). "Thus, SOX10 and SOX9 are functionally antagonistic regulators of melanoma development." (PMID 25629959, 2015). "In contrast, SOX9 may function as a tumor suppressor, at least in some melanomas." (PMID 24188461, 2013). "Within the SOX gene family, SOX4, SOX5, SOX9 and SOX10 are established key regulators in melanoma cells establishment and function." (PMID 40866912, 2025). "It has been demonstrated that SOX9 reduced PRAME expression, reinstating melanoma cell sensitivity to RA." (PMID 38338862, 2024). "These over-expressed proteins shifted YUMM2.1 cells toward a mesenchymal melanoma transcriptional state related to the switch between SOX10 and SOX9 expression observed in human melanomas." (PMID 38245503, 2024). "In order to evaluate the phenotypic diversity of our samples, we mapped the expression profile of key melanoma cell-state regulatory genes such as the NGFR, RXRG, MITF, SOX10, SOX9 and AXL genes." (PMID 36765773, 2023).